RNU7-193P (RNA, U7 small nuclear 193 pseudogene)
Gene: Small nuclear RNA gene on chromosome 10 (43,458,065 to 43,458,129, forward strand). Ensembl gene ENSG00000252532.
Homologues: Orthologues: chimpanzee U7 (100% identical), macaque U7 (80% identical). Paralogues in human: RNU7-13P (83% identical), RNU7-18P (80% identical), RNU7-28P (80% identical), RNU7-41P (80% identical), RNU7-6P (80% identical), RNU7-8P (80% identical), RNU7-22P (78% identical), RNU7-25P (78% identical), RNU7-45P (78% identical), RNU7-113P (77% identical), RNU7-11P (77% identical), RNU7-12P (77% identical), and 141 more.